MDH2 (malate dehydrogenase 2)
Description:
Mitochondrial malate dehydrogenase that catalyzes the reversible conversion of malate to oxaloacetate using NAD(+) as a cofactor. Plays a central role in the tricarboxylic acid (TCA) cycle contributing to cellular respiration and energy production via the mitochondrial electron transport chain. Also participates in the malate-aspartate NADH shuttle, facilitating transfer of reducing equivalents between cytosol and mitochondria to maintain redox balance (NAD(+)/NADH homeostasis) and support metabolic flux between compartments (By similarity). In addition to its metabolic role, binds to RNA in cells, associating with cytosolic RNAs including tRNAs and mRNAs.
Synonyms: DEE51; EIEE51; M-MDH; MDH; MGC:3559; MOR1
Tractability: Small molecule: a structure with a bound ligand is known; it has a high-quality binding pocket. PROTAC: ubiquitination databases record sites on it; its protein half-life has been measured; a small molecule that binds it is known.
Target class: Enzyme; Oxidoreductase
Gene: Protein-coding gene on chromosome 7 (76,048,050 to 76,067,508, forward strand). Ensembl gene ENSG00000146701.
Subcellular location: Mitochondrion matrix
Subcellular location (Human Protein Atlas): Mitochondria
Pathways (Reactome):
Metabolism: Citric acid cycle (TCA cycle); Malate-aspartate shuttle
Metabolism of proteins: Mitochondrial protein degradation
Gene Ontology:
Molecular function: L-malate dehydrogenase (NAD+) activity; RNA binding; catalytic activity; identical protein binding; L-malate dehydrogenase (NADP+) activity; malate dehydrogenase activity; oxidoreductase activity; oxidoreductase activity, acting on the CH-OH group of donors, NAD or NADP as acceptor
Biological process: aerobic respiration; malate metabolic process; malate-aspartate shuttle; tricarboxylic acid cycle; gluconeogenesis
Cellular component: extracellular exosome; mitochondrial matrix; mitochondrion; nucleus; membrane
Genetic constraint (gnomAD): Loss-of-function variants: 25 observed, 35.49 expected, observed/expected ratio (o/e) 0.7, 90% interval 0.51 to 0.98. The upper end of that interval is the gene's LOEUF score, 0.98, which puts it in group 4 of 6, group 1 being the genes least tolerant of losing a copy. Missense variants: 432 observed, 451.8 expected, observed/expected ratio (o/e) 0.96, 90% interval 0.88 to 1.03. Synonymous variants: 193 observed, 192.54 expected, observed/expected ratio (o/e) 1, 90% interval 0.89 to 1.13.
Homologues: Orthologues: chimpanzee MDH2 (99% identical), macaque MDH2 (98% identical), mouse Mdh2 (95% identical), pig MDH2 (94% identical), rat Mdh2 (94% identical), dog MDH2 (93% identical), guinea pig MDH2 (93% identical), rabbit MDH2 (86% identical), zebrafish mdh2 (85% identical), tropical clawed frog mdh2 (84% identical), Drosophila melanogaster Mdh2 (59% identical), Caenorhabditis elegans mdh-2 (57% identical), and 2 more. Paralogues in human: LDHA (25% identical), LDHAL6A (25% identical), LDHAL6B (25% identical), LDHC (24% identical), LDHB (24% identical).
Diseases named in the same sentence as MDH2 in open-access papers:
MDH2 is named in the same sentence as 91 diseases in open-access papers, as found by Europe PMC text mining. Sharing a sentence is not in itself a finding about the gene and the disease. The quoted sentences say what the papers report.
ovarian carcinoma (12 papers, 2022 to 2025). A malignant neoplasm originating from the surface ovarian epithelium. "Furthermore, MDH2 palmitoylation was associated with enhanced mitochondrial respiration to promote ovarian cancer growth." (PMID 36909239, 2023). "ZDHHC18 has been reported to catalyze the palmitoylation of MDH2 and promote the development of ovarian cancer." (PMID 39913299, 2025). "Recent studies have unveiled the critical role of MDH2 in various cancers, including glioblastoma, endometrial carcinoma, and ovarian cancer." (PMID 41179294, 2025). "The OAA produced by MDH2 rewires the fueling of the respiratory chain and the TCA cycle, MDH2 promotes the growth of ovarian cancer by activating mitochondrial respiration." (PMID 39138167, 2024). "ZDHHC18 functions as a palmitoyltransferase for MDH2, promoting the formation of ovarian cancer by maintaining mitochondrial respiration and reinstating the growth and clonogenic potential of ovarian cancer cells." (PMID 39148124, 2024). "Silencing zDHHC18 suppressed MDH2 S‐acylation, reducing mitochondrial respiration and proliferation of ovarian cancer cell lines." (PMID 39429488, 2024). "Re‐expression of wild‐type MDH2, but not of its S‐acylation‐deficient Cys138S mutant, restored mitochondrial respiration and enhanced the growth and clonogenicity of ovarian cancer cells in vitro and in nude mice injected with MDH2‐knockout A2780 cells." (PMID 39429488, 2024). "Interestingly, while investigating its role in ovarian cancer metabolism, MDH2 was found to be palmitoylated on Cys138 resulting in increased activity of the enzyme." (PMID 36909239, 2023). "Silencing MDH2 suppresses mitochondrial respiration and ovarian cancer cell proliferation, indicating that targeting ZDHHC18-mediated MDH2 palmitoylation represents a potential therapeutic strategy for EOC." (PMID 40977744, 2025).
prostate carcinoma (11 papers, 2015 to 2025). A carcinoma that arises from epithelial cells of the prostate gland. "Aberrant MDH2 function has been linked to cancers such as paragangliomas, endometrial carcinoma, and prostate cancer." (PMID 41179294, 2025). "Mutations in the MDH2 gene are related to several cancers, including uterine cancer, prostate cancer, pheochromocytoma, and other paragangliomas." (PMID 31817761, 2019). "The elevation of MDH2 expression has been implicated in prostate cancer resistance to docetaxel-chemotherapy." (PMID 27611801, 2016). "MDH2 silencing reduces prostate cancer cell growth and enhances docetaxel sensitivity by causing metabolic inefficiency; high MDH2 expression is associated with shorter recurrence-free survival and treatment tolerance in prostate cancer patients." (PMID 41179294, 2025). "Notably, high MDH2 expression has been associated with shorter recurrence-free survival and increased chemotherapy tolerance in prostate cancer patients." (PMID 41179294, 2025). "Moreover, the overexpression of the gene MDH2 was associated with shorter relapse-free survival in prostate cancer patients who underwent chemotherapy." (PMID 37601653, 2023). "In addition, overexpression of MDH2 is associated with drug resistance and short relapse-free survival in patients with prostate cancer." (PMID 34829545, 2021). "Elevation of MDH2 expression has been implicated in docetaxel resistance in prostate cancer cells." (PMID 27611801, 2016). "Mechanistically, MDH2 silencing has been shown to inhibit prostate cancer cell proliferation and enhance docetaxel sensitivity by inducing metabolic inefficiency." (PMID 41179294, 2025). "The knockdown of MDH2 in prostate cancer cell lines decreased cell proliferation, increased sensitivity to the chemotherapy drug docetaxel, and affected signaling pathways and metabolic efficiency by influencing JNK signaling and oxidative metabolism." (PMID 37601653, 2023). "In prostate cancer cells, MDH2 knockdown inhibits proliferation and enhances docetaxel sensitivity through induced metabolic inefficiency." (PMID 34829545, 2021). "Although FH and MDH2 activities were comparable among prostate cancer and benign cell lines at the basal condition, interestingly, Alternol enhanced their activities in prostate cancer cells but not in BPH1 cells." (PMID 33224877, 2020). "It is also likely that through the JNK pathway, MDH2 is able to lend docetaxel resistance in prostate cancer cells." (PMID 31817761, 2019). "The exception is MDH2, protein levels of which continue to increase in the second shift during prostate cancer progression." (PMID 29563510, 2018). "Further, stable knockdown of MDH2 via shRNA in prostate cancer cell lines decreased cell proliferation and increased docetaxel sensitivity." (PMID 29563510, 2018). "Few data are known about prostate cancer metabolism but a recent study has shown that patients bearing mitochondrial malate dehydrogenase 2 (MDH2) overexpression have shorter relapse free survival after neoadjuvant chemotherapy." (PMID 27542265, 2016). "MDH2 knockdown using shRNA enhanced docetaxel sensitivity through activation of JNK signaling in prostate cancer cells." (PMID 27611801, 2016). "MDH2 was observed to be overexpressed in doxorubicin-resistant uterine cancer cells and prostate cancer cells and may contribute to drug resistance in disease models." (PMID 31817761, 2019). "Moreover, overexpression of MDH2 in clinical prostate cancer has resulted in shortened periods of relapse-free survival after exposure to chemotherapy." (PMID 27611801, 2016). "Thus, development of MDH2-specific chemical inhibitors could be of great benefit against progressed prostate cancer, as well as for prevention of cardiotoxicity during chemotherapy." (PMID 29563510, 2018).
paraganglioma (9 papers, 2017 to 2023). A benign or malignant neoplasm arising from paraganglia located along the sympathetic or parasympathetic nerves. "Disruption of the Krebs cycle is a hallmark of cancer, and MDH2 has been recently identified as a novel pheochromocytoma and paraganglioma susceptibility gene." (PMID 27989324, 2017). "Altered metabolism caused by mutations in MDH2 has been implicated in various cancers, including an association with metastasis in pheochromocytomas and paragangliomas, and a germline splice site mutation leading to reduced MDH2 activity has been identified in a familial case of paraganglioma." (PMID 38136396, 2023). "A loss-of-function germline mutation in MDH2 was observed in paraganglioma." (PMID 36159820, 2022). "Similar to succinate and fumarate accumulation, which leads to enzymatic inhibition of multiple α-KG-dependent dioxygenases in the Krebs cycle, a new germline mutation in MDH2 (malate dehydrogenase 2) has been found to cause phaeochromocytoma/paraganglioma (with possible metastasis)." (PMID 29166454, 2017). "In subjects’ paragangliomas, loss of heterozygosity was associated with loss of MDH2 activity, but surprisingly, this did not lead to malate accumulation." (PMID 27989324, 2017). "Among the relatives of this patient, two out of five carried the mutant MDH2 gene although they showed no symptoms of paragangliomas or other diseases associated with mutations in this gene." (PMID 28187001, 2017). "Mutations in some genes have been found only in single patients or families (e.g., MEN1, EGLN1, EGLN2, MDH2, IDH1, BAP1, BRAF); therefore, their role in the formation of paragangliomas/pheochromocytomas cannot be reliably confirmed." (PMID 28187001, 2017).
pheochromocytoma (9 papers, 2017 to 2023). "Cluster 1 PPGLs include pheochromocytomas and abdominal paragangliomas carrying the highest risk of metastatic spread, especially the TCA cycle aberrant tumors carrying genetic variants in enzymes regulating the TCA cycle, including SDHA, SDHB, SDHAF2, FH, MDH2, ISH1 and SLC25A11." (PMID 35205664, 2022).
diabetes (7 papers, 2012 to 2024). "Typically, a reduction in Mdh2 expression is observed in individuals with diabetes as it can impact insulin release, and Mdh2 mutations have been observed in families that exhibit transgenerational hyperglycemia." (PMID 39000422, 2024). "MDH2 has also been shown to play a critical role in insulin secretion, and mutations in this gene are known to cause diabetes." (PMID 39324112, 2024). "A study identified MDH2 as a novel diabetes gene whose heterozygous mutation causes hyperglycemia in families with multigenerational diabetes." (PMID 36187097, 2022). "The differential expression of PFKM, GAPDH, ACO2, and MDH2 in the urinary exosomes of diabetic patients can serve as potential biomarkers for diabetes monitoring, providing a promising method for noninvasive diabetes diagnosis." (PMID 36187097, 2022). "Furthermore, the following genes are involved in diabetes and insulin signaling: MDH2, PPP1CA and HRAS." (PMID 26938218, 2016). "In diabetic patients, aerobic oxidative metabolism is reduced, and the expression of aerobic oxidative metabolism-related proteins PFKM, GAPDH, ACO2, and MDH2 in urinary exosomes is reduced, which may become potential biomarkers for monitoring changes in diabetes." (PMID 36187097, 2022).
Encephalopathy (6 papers, 2017 to 2025). Encephalopathy is a term that means brain disease, damage, or malfunction. "For example, in Early-Onset Severe Encephalopathy, MDH2 mutations cause abnormal accumulation of its substrates malate and fumarate." (PMID 40730642, 2025). "Although this c.196G>A; p.(Ala66Thr) variant has been associated with severe encephalopathy, several other variants in MDH2 have been reported in PPGLs that point to its pathogenicity." (PMID 39596125, 2024). "Inherited MDH2 deficiency is an ultra-rare metabolic disease caused by bi-allelic pathogenic variants in the MDH2 gene, resulting in early-onset encephalopathy, psychomotor delay, muscular hypotonia and frequent seizures." (PMID 38425868, 2024). "MDH2 dysfunction causes an energy deficit affecting many organs, leading to symptoms including early-onset encephalopathy, frequent seizures, psychomotor delay, and muscular hypotonia, although symptom onset and affected organs may vary by individual." (PMID 38425868, 2024). "Bi-allelic mutations in MDH2 were also reported to cause the early-onset of severe encephalopathy." (PMID 36159820, 2022). "Similarly, mutations in MDH2 cause early-onset severe encephalopathy in HEK293 cells because of deleterious MDH2 variants." (PMID 34884868, 2021).
glioblastoma (5 papers, 2022 to 2025). The most malignant astrocytic tumor (WHO grade IV). "Inhibiting MDH2 in glioblastoma stem cells enhanced the effectiveness of dasatinib, a multi-kinase inhibitor, suggesting a potential therapeutic approach for targeting stem-like tumor cells by reprogramming their metabolism." (PMID 39759516, 2024). "Furthermore, studies have found that glioblastoma stem cells responsible for tumor growth and drug resistance rely on high activity of malate dehydrogenase 2 (MDH2) to maintain their malignant phenotype." (PMID 40255400, 2025). "Meanwhile, another recent study showing the forced expression of malate dehydrogenase 2(MDH2) raised m6A levels and suppressed ALKBH5 activity in glioblastoma stem cells, which could be restored by alpha-ketoglutarate supplementation." (PMID 39759516, 2024).
lung carcinoma (5 papers, 2018 to 2025). "The association of MDH1 and MDH2 have been reported in several cancers such as pancreatic and lung cancers." (PMID 37242466, 2023). "In this study, we synthesized compound 50, a potent MDH1/MDH2 dual inhibitor that suppressed MAS function in A549 lung cancer cells." (PMID 37242466, 2023). "The expression levels of MDH1 and MDH2 are high in patients with lung cancer." (PMID 37242466, 2023). "MDH1 and MDH2 enzymes play an important role in the survival of lung cancer." (PMID 37242466, 2023). "MDH2 knockdown in lung cancer cell lines inhibited cell proliferation." (PMID 35178152, 2022). "MDH2 expression levels were also higher in lung cancer tissues than in normal tissues." (PMID 35178152, 2022). "AC020978 also binds to malate dehydrogenase 2 (a mitochondrial enzyme involved in the TCA cycle and the malate–aspartate shuttle, MDH2), activates the PI3K–AKT pathway, and promotes lung cancer cell metastasis." (PMID 40746614, 2025). "Furthermore, our study concurs with the finding that MDH1, but not MDH2, is required for proliferation of lung cancer cell lines." (PMID 29452638, 2018).
breast cancer (4 papers, 2021 to 2025). A primary or metastatic malignant neoplasm involving the breast. "We aimed to elucidate the oncogenic role of MDH2 in breast cancer and to evaluate its potential as a diagnostic, therapeutic, and prognostic biomarker." (PMID 41179294, 2025). "Despite the emerging evidence of MDH2’s role in cancer, the underlying mechanisms by which MDH2 promotes breast cancer growth remain poorly understood." (PMID 41179294, 2025). "Kaplan-Meier survival analysis further demonstrated that elevated MDH2 expression is strongly associated with poor prognosis in breast cancer patients." (PMID 41179294, 2025). "This small sequencing study identified a set of strong candidate variants for inherited predisposition for breast cancer recurrence, including MDH2, which should be pursued in other resources." (PMID 38136396, 2023). "One variant in MDH2 showed strong evidence for segregation with recurrent breast cancer, as well as breast cancer, in the extended pedigree in which it was discovered." (PMID 38136396, 2023). "A rare variant in MDH2 was found to segregate with breast-cancer-affected relatives in one extended pedigree." (PMID 38136396, 2023). "Interestingly, MDH2 overexpression upregulated several genes associated with breast cancer metastasis (IL13RA2, MMP3, PTGS1, SYK, VCAN, and FLT1) and downregulated several genes associated with metastasis suppression (NOTCH3 and HTRA3)." (PMID 41179294, 2025). "Malate dehydrogenase 2 (MDH2), a key enzyme in the tricarboxylic acid cycle, has been implicated in several malignancies, but its role in breast cancer tumorigenesis and progression remains unclear." (PMID 41179294, 2025). "Therefore, we propose that MDH2, which is implicated in cancer metabolism, influences breast cancer development by modifying the tumor immune microenvironment through the release of metabolites such as adenosine and linoleic acid." (PMID 41179294, 2025). "Given that MDH2 is implicated in cell migration and metabolism, we conducted correlation analyses on DEGs associated with breast cancer metastasis and 62 differential metabolites to systematically and comprehensively disclose the regulatory mechanisms of MDH2 on these biological processes." (PMID 41179294, 2025). "This small sequencing study, using a powerful approach based on recurrent breast cancer cases from high-risk pedigrees, identified a set of strong candidate variants for inherited predisposition for breast cancer recurrence, including MDH2, which should be pursued in other resources." (PMID 38136396, 2023). "Given the transcriptomic data suggesting MDH2’s involvement in cell migration and metabolism, we explored the migratory and metabolic functions of MDH2 in breast cancer." (PMID 41179294, 2025). "In this study, we leveraged gene expression profiling and comprehensive analysis of TCGA data to elucidate the role of MDH2 in breast cancer." (PMID 41179294, 2025). "Collectively, these results indicate that MDH2 is overexpressed in breast cancer at both the transcriptional and translational levels, suggesting that the MDH2 gene plays a crucial role in breast cancer pathogenesis." (PMID 41179294, 2025). "Our study reveals that altered MDH2 expression significantly modifies 62 metabolites in breast cancer, primarily amines, amino acids, nucleosides, and other classes." (PMID 41179294, 2025). "Data from the TCGA database indicate that MDH2 expression is abnormally elevated in advanced breast cancer." (PMID 41179294, 2025). "In vitro studies have revealed that silencing MDH2 effectively curtails the proliferative and migratory capacities of breast cancer cells." (PMID 41179294, 2025). "At the protein level, immunohistochemical analysis from the HPA database showed that MDH2 protein was markedly overexpressed in breast cancer tissues (ductal and lobular carcinomas) compared to normal breast tissue." (PMID 41179294, 2025).